ROR2 (ROR family WNT receptor 2)
Diseases named in the same sentence as ROR2 in open-access papers (continued):
Sharing a sentence is not in itself a finding about the gene and the disease.
breast carcinoma (32 papers, 2010 to 2025). "High-level expression of ROR2 was lowest in the HR- HER2- subtype of breast cancers and higher ROR2 expression was associated with worse EFS in HER2 + patients with minimal residual disease after therapy (RCB-0/I)." (PMID 37029329, 2023). "ROR1 and ROR2 are Type 1 tyrosine kinase-like orphan receptors for Wnt5a that are associated with breast cancer progression." (PMID 37029329, 2023). "In contrast to ROR1, ROR2 was not only found to be highly expressed in basal-like but in 87% of all breast cancers, and high levels were associated with shorter overall survival." (PMID 34911552, 2021). "Now, we explored the molecular mechanisms underlying these observations and showed that ROR2 confers an aggressive phenotype to breast cancer cells that is linked to basal-like features and a high invasive potential." (PMID 34911552, 2021). "High ROR1 or high ROR2 was associated with breast cancer subtypes." (PMID 37029329, 2023). "Both COL3A1 and ROR2 have been implicated in breast cancer pathogenesis." (PMID 36190948, 2022). "Similarly, ROR2 expression correlates with tumor stage and metastasis in lung, cervical, and breast cancer and is associated with worse OS in several types of cancer." (PMID 34319035, 2021). "In line with our hypothesis, analysis of the progression-free survival of 1067 breast cancer patients from the TCGA database confirmed the prognostic relevance of ROR2 and its association with aggressive disease." (PMID 34911552, 2021). "Together, our data suggest that ROR2 may represent a novel indicator of poor prognosis in BC patients, and might serve as a potential diagnostic biomarker and therapeutic target in breast cancer." (PMID 32614787, 2020). "Moreover, we showed in the gene expression data of breast cancer patients that the Ror2/Wnt module-based gene signature is associated with metastasis-free survival." (PMID 28695110, 2017). "Interestingly, both Ror1 and Ror2 have been suggested as receptors for Wnt5a, have been linked to breast cancer progression and their expression was previously observed in breast cancer brain metastasis." (PMID 28695110, 2017). "We also saw significant upregulation of many genes with notable associations to metastasis such as ROR2 whose overexpression was shown to promote breast cancer cell invasion and increased expression was associated with worse overall survival in breast cancer patients." (PMID 35318435, 2022). "These included breast cancer, where 87% of the tumors exhibited ROR2 expression, glioblastoma with over 90% ROR2-positive tumors, and n NB, where 80% of the tumors showed ROR2 presence." (PMID 38601081, 2024). "We examined the relationship between gene expression of ROR1 and/or ROR2 and outcomes in breast cancer patients enrolled in the “Investigation of Serial Studies to Predict Your Therapeutic Response with Imaging And Molecular Analysis 2” (I-SPY2 TRIAL) study." (PMID 37029329, 2023). "High ROR1 or high ROR2 distinctly identified subsets of breast cancer patients with adverse outcomes." (PMID 37029329, 2023). "To study the extracellular spreading of ROR1 and ROR2 in breast cancer, we chose human MCF-7 and MDA-MB-231 as well as murine 4T1 breast cancer cells as model cell lines." (PMID 37430307, 2023). "In this study we detected the Wnt co-receptors ROR1 and ROR2 on EVs from breast cancer cell lines and patients and thus identified a novel mode for spreading Wnt/ROR signaling across tissues." (PMID 37430307, 2023). "While both ROR1 and ROR2 are only detectable at low levels in healthy tissue, they are found overexpressed in breast cancer primaries as well as metastases." (PMID 37430307, 2023). "Using flow cytometry we detected lEVs carrying ROR1 as well as ROR2 in peripheral blood of breast cancer patients." (PMID 37430307, 2023). "In breast cancer cells, cellular expression of ROR1 and ROR2 has been linked to tumor invasion via Rho/Rock signaling." (PMID 37430307, 2023).
breast carcinoma (continued). "In order to confirm that EVs can indeed transport ROR1 and ROR2, we isolated the main EV subpopulations, LOs, lEVs, and sEVs, from the conditioned medium of the three breast cancer cell lines by using differential ultracentrifugation." (PMID 37430307, 2023). "Recent studies have revealed that this applies also to ROR1 and ROR2 as both have been observed to be heterogeneously expressed in pancreatic and mammary tumors in vivo." (PMID 37430307, 2023). "The PI3K/Akt pathway was shown to be activated by ROR2 and to be an effector of its oncogenic functions in osteosarcoma, colon, breast cancer, and myeloma cells." (PMID 34774050, 2021). "In vitro studies have revealed a stimulatory function of ROR2 on breast cancer cell invasion and migration, mostly through induction of an EMT-like cancer cell phenotype." (PMID 34911552, 2021). "ROR2 mediates epithelial-to-mesenchymal transition (EMT) in breast cancer through p38/mitogen-activated protein kinase." (PMID 34319035, 2021). "Previously, we had described a gene expression signature comprising 76 genes regulated by the WNT co-receptor ROR2 which grouped primary breast cancer patients into two clusters with significant differences in MFS." (PMID 34911552, 2021). "ROR2 also regulates the epithelial-mesenchymal transition phenotype of breast cancer cells via the activation of the MAPK/p38 signaling pathway." (PMID 34440262, 2021). "Instead, a high expression of the alternative WNT receptor ROR2 was observed, in particular in breast cancer brain metastases." (PMID 34911552, 2021). "Taken together, our study revealed a novel auto-stimulatory loop in which ROR2 triggers the expression of its own ligand, WNT11, resulting in enhanced tumor invasion associated with breast cancer metastasis." (PMID 34911552, 2021). "A particularly high percentage of ROR2-positive tumors was found in breast cancer (87%), glioblastoma (>90%), and neuroblastoma (80%)." (PMID 33445713, 2021). "Although the results did not quite reach significance due to the limited number of patient samples, the results do indicate that WNT11/ROR2 exerts an unfavorable role in brain metastasis of breast cancer patients in vivo." (PMID 34911552, 2021). "Taken together, these results imply that WNT11 is able to activate tumor-promoting signaling pathways in breast cancer cells via its interaction with ROR2." (PMID 34911552, 2021). "The receptor tyrosine kinase like orphan receptor 2 (ROR2) has been implicated in the pathogenesis of a variety of human cancers, including breast cancer." (PMID 32614787, 2020). "In this study, we show that down-regulation of ROR2 significantly inhibits breast cancer cell proliferation in vitro, and BC tumor growth in vivo, and that the mechanism involves the phosphatidylinositol 3-kinase (PI3K)/AKT signaling pathway." (PMID 32614787, 2020). "Here, we analyzed the clinical significance of ROR2 in breast cancer (BC) progression, and its function in the regulation of BC cell proliferation and growth." (PMID 32614787, 2020). "In conclusion, our results show that the expression of ROR2 is increased in human breast cancer tissues, and correlates with the DFS rates in BC patients." (PMID 32614787, 2020). "The ROR2 expression is increased in breast cancer tissues compared to corresponding pericarcinomatous tissues." (PMID 32614787, 2020). "For instance, Wnt5a and Wnt5b were found to be overexpressed in basal-like MDA-MB-231 cells compared to less aggressive LumA MCF-7 cells and their expression levels were also elevated together with Ror1/Ror2 in breast cancer brain metastases." (PMID 28695110, 2017).
breast carcinoma (continued). "In summary, results of this study indicate a role of a newly defined Ror2/Wnt module in breast cancer progression and present a link between Ror2 expression and increased cell invasiveness." (PMID 28695110, 2017). "The mixed distribution of breast cancer subtypes across the four patient clusters in the dendrogram motivated us to explore the MFS within the individual subtypes in regard to the Ror2/Wnt module expression patterns." (PMID 28695110, 2017). "The identified 84 genes in the Ror2/Wnt module were used as a pathway-based gene signature to assess prognostic power for metastasis development in breast cancer." (PMID 28695110, 2017). "Here, we further demonstrated that the expression of Ror2/Wnt module genes has prognostic power in this breast cancer subtype." (PMID 28695110, 2017). "Similar observations have not only been made for MCF-7, but also for Her2-positive SK-BR-3 cells, thus pointing to a general effect of Ror2 on breast cancer cell invasiveness." (PMID 28695110, 2017). "We considered the members of the Ror2/Wnt module to be candidate genes of the non-canonical Wnt pathway that confer an aggressive phenotype to MCF-7 breast cancer cells after Ror2 overexpression." (PMID 28695110, 2017). "In conclusion, in this study we explored effects of Wnt5a and Ror2 perturbations in the ER-positive breast cancer cell line MCF-7 on the phenotypic and gene expression levels." (PMID 28695110, 2017). "Previously, we demonstrated overexpression of the homologues receptors ROR1 and ROR2 in brain metastasis of breast cancer patients." (PMID 26862065, 2016). "Given the fundamental importance of lineage stability in epithelial homeostasis, our results suggest that disruptions in Wnt/Ror2 signaling may contribute to aberrant fate transitions relevant to breast cancer progression." (PMID 40060578, 2025). "We hypothesize that prognostic value also may be observed in stratifying breast cancers with respect to their relative levels of ROR1 and/or ROR2 in the context of residual disease or associated clinical subtype." (PMID 37029329, 2023). "Using the annotated I-SPY2 transcriptome data from a cohort of nearly 1000 patients with newly diagnosed high-risk early breast cancer, we found that high-level pretreatment expression of ROR1 or ROR2 had a distinct subtype-specific association with adverse risk." (PMID 37029329, 2023). "The results for ROR2 expression significantly extend the prior observations that ROR2 signaling also may contribute to breast cancer progression and/or tissue invasiveness." (PMID 37029329, 2023). "Interestingly, breast cancer patients expressing ROR2 had shorter overall survival than those harboring tumors without ROR2 expression." (PMID 37492224, 2023). "Having detected high levels of vesicular ROR1 and ROR2 expression in breast cancer cells, we asked whether RORs can be transported to surrounding cells via EVs." (PMID 37430307, 2023). "This study highlights the potential prognostic value in assessing the levels of ROR1 and/or ROR2 in untreated high-risk early-stage breast cancer and justifies further studies to evaluate the biology and possible value of targeting ROR1 and ROR2 with investigational treatments." (PMID 37029329, 2023). "ROR2 has been shown to act as an oncogene to promote breast cancer progression." (PMID 36190948, 2022). "WNT5B has been shown to interact with ROR2 in osteosarcoma, while preliminary results indicate that WNT11 could be a ligand of ROR2 in breast cancer." (PMID 35246138, 2022). "We modulated the expression of ROR2 in human breast cancer cells and characterized their gene and protein expression by RNA-Seq, qRT-PCR, immunoblots and reverse phase protein array (RPPA) combined with network analyses to understand the molecular basis of ROR2 signaling in breast cancer." (PMID 34911552, 2021). "However, overexpression of ROR2 inhibited Akt phosphorylation in two breast cancer cell lines and two pancreatic cancer cell lines." (PMID 34774050, 2021).
breast carcinoma (continued). "Moreover, we had detected high expression levels of ROR2 in breast cancer brain metastases, suggesting its active involvement in tumor progression." (PMID 34911552, 2021). "Concordantly, in breast cancer cells ROR2 overexpression augmented ROR1 levels." (PMID 33445713, 2021). "Indeed, gene expression data from the TCGA database pointed to a negative correlation of ROR2 expression with an active canonical WNT signature in breast cancer patients, suggesting that the inhibitory effect of ROR2 also occurs in vivo." (PMID 33445713, 2021). "Likewise, the same effect was seen after specific knockdown of RHOA, ROCK1 and ROCK2 by siRNA in all three ROR2-overexpressing breast cancer cell lines." (PMID 34911552, 2021). "To test whether the induction of WNT11 is specific for MCF-7 cells or a general phenomenon in breast cancer, we overexpressed ROR2 in different human breast cancer cell lines." (PMID 34911552, 2021). "Furthermore, ROR2 facilitates breast cancer progression by regulating the expression of PI3K/AKT and apoptotic signaling genes." (PMID 34440262, 2021). "Indeed, ROR2 expression was found to correlate with tumor stage and/or lymph node metastasis in lung, cervical, and breast cancer." (PMID 33445713, 2021). "So far, available evidence indicates that ROR2 acts as an oncogene in breast cancer." (PMID 34911552, 2021). "Together, these data indicate that ROR2 acts as an oncogenic gene in BC, and suggest that the ROR2/PI3K/AKT regulatory network might contribute to breast cancer progression." (PMID 32614787, 2020). "In the present study, we also observed an increased expression of ROR2 in breast cancer tissues." (PMID 32614787, 2020). "Furthermore, breast cancer patients expressing Ror1 and Ror2 have been reported to show a poor survival." (PMID 28695110, 2017). "Owing to the synchronous highly expression pattern of Wnt5a in breast cancer, gastric cancer, non-small-cell lung cancer, prostate cancer, we predict that Wnt5a and ROR2 may act as co-effector in certain specific tumors." (PMID 29213214, 2017). "To test this hypothesis, we investigated the fate of the oncogenic transmembrane Wnt tyrosine kinase-like orphan receptor 1 and 2 (ROR1, ROR2) delivered via distinct EV subpopulations to breast cancer cells and aimed to unravel their impact on tumor progression." (PMID 37430307, 2023). "Therefore, we examined the expression of genes that may be upregulated in breast cancer cells through activation of ROR1 or ROR2 signaling." (PMID 37029329, 2023). "However, based on the functional data presented in the previous chapters, this seems surprising since evidence has accumulated for several solid tumors that clearly highlight ROR2 as an oncogene in these entities (e.g., breast cancer, lung cancer, and sarcoma)." (PMID 33445713, 2021). "However, very little is known about the expression and function of ROR2 in breast cancer." (PMID 32614787, 2020). "However, silencing ROR2 in human breast cancer cell lines decreased both β-catenin-dependent and β-catenin-independent targets, suggesting that ROR2 may be involved in both β-catenin-dependent and β-catenin-independent Wnt signaling pathways." (PMID 28491097, 2017). "The three antigens separated breast cancer patients from healthy individuals with an AUC of 0.663 (95% CI: 0.504–0.821) for ROR1, 0.732 (95% CI: 0.586–0.878) for ROR2 and 0.652 (95% CI 0.489–0.814) for EpCAM." (PMID 37430307, 2023). "Taken together, we show for the first time that ROR2 can trigger an autocrine, invasion-promoting signaling response via RHO/ROCK by inducing expression of its own ligand, WNT11, in human breast cancer." (PMID 34911552, 2021). "Several clinical trials are currently being conducted to evaluate the effectiveness of CTAs, such as NY-ESO-1, MAGE, MSLN, PRAME, PSCA, ROR2 and WT1, as treatment targets in breast cancers and other solid tumours." (PMID 34359776, 2021).
breast carcinoma (continued). "WNT11 binds to the CRD of ROR2 and mediates WNT/PCP signaling via the RHO/ROCK pathway that confers an aggressive phenotype to breast cancer cells." (PMID 34911552, 2021). "Together, our results indicate that ROR2 acts as an oncogenic gene in breast cancer, and suggest that the ROR2/PI3K/AKT regulatory network contributes to breast cancer progression." (PMID 32614787, 2020). "Examining BT549 (breast cancer) and U2OS (osteosarcoma) cells as examples, which are also non-ciliated, we first confirmed that siRNA against either Ror2 or IFT20 also reduced the invasiveness of these tumor cells." (PMID 28127051, 2017). "To further investigate the impact of ROR1/2 overexpression in breast cancer cells, we transfected both the luminal A breast cancer cell line MCF-7 and the ERBB2/HER-2+ cell line SK-BR-3 with a ROR2 construct." (PMID 26862065, 2016). "In most of the cell lines examined, Ror1 seemed to have a higher or similar expression level compared with Ror2, except in MCF-7 breast cancer cells." (PMID 20587074, 2010). "Beyond HER2 and TROP2, alternative targets being evaluated for novel breast cancer ADCs in phase I‐II trials include HER3, B7‐H3, B7‐H4, CD166, folate receptor‐α, LIV‐1, nectin‐4, ROR1 (NCT04504916), and ROR2 (NCT03504488)." (PMID 41361931, 2025). "Of note, we did not detect a significant amount of ROR1 or ROR2 on LOs secreted by the investigated breast cancer cells." (PMID 37430307, 2023). "Using breast cancer cell lines and patient samples, this study identified small and large EVs as a novel mode of transportation for spreading ROR1 and ROR2 within the local tumor microenvironment as well as the hematological system where they can be used as cancer biomarkers." (PMID 37430307, 2023). "Although not correlated with pCR, high-level expression of ROR1 or ROR2 distinctly identified breast cancer patients with different tumor subtypes with adverse outcomes." (PMID 37029329, 2023). "We found that expression of ROR2 was lowest in HR- HER2- breast cancer, highest in the HR + HER2 + subtype, and did not correlate with pCR." (PMID 37029329, 2023). "In the present study, we used breast cancer cell lines as well as patient samples to investigate whether the two Wnt co-receptors ROR1 and ROR2 can be spread via EVs." (PMID 37430307, 2023). "For instance, IQGAP3, EPHB1, ROR2 and RCC2 were demonstrated to obviously promote cell migration, invasion, and epithelial-to-mesenchymal transition in hepatocellular carcinoma, medulloblastoma and breast carcinoma, respectively." (PMID 34922560, 2021). "Considering the ambiguous role of WNT5A which has been described to act both as an oncogene as well as a tumor suppressor in breast cancer, it is still unclear whether other WNT ligands exist that can activate ROR2 signaling." (PMID 34911552, 2021). "In detail, ROR2 overexpression promotes PI3K activation and AKT phosphorylation, followed by the downregulation of p21 and upregulation of cyclin D1 and PDK1, resulting in increased proliferation and survival of breast cancer cells." (PMID 34440262, 2021). "We had previously shown that overexpression of ROR2 does not affect the levels or localization of β-catenin in breast cancer cells and thus does not activate canonical WNT signaling." (PMID 34911552, 2021). "In contrast, WNT4 was not differentially expressed upon ROR2 overexpression in the investigated breast cancer cell lines." (PMID 34911552, 2021). "Whether ROR1 can have a similar effect with ROR2 on breast cancer stem cell and what signaling pathway(s) are activated by ROR1 in breast cancer stem cells remains unknown." (PMID 28491097, 2017). "In summary, this Ror2/Wnt module highlights the importance of non-canonical Wnt signaling, and in addition to the Ror2 targets it reveals further key genes relevant for breast cancer progression." (PMID 28695110, 2017).